HPGD (15-hydroxyprostaglandin dehydrogenase)
Description:
Catalyzes the NAD-dependent dehydrogenation (oxidation) of a broad array of hydroxylated polyunsaturated fatty acids (mainly eicosanoids and docosanoids, including prostaglandins, lipoxins and resolvins), yielding their corresponding keto (oxo) metabolites. Decreases the levels of the pro-proliferative prostaglandins such as prostaglandin E2 (whose activity is increased in cancer because of an increase in the expression of cyclooxygenase 2) and generates oxo-fatty acid products that can profoundly influence cell function by abrogating pro-inflammatory cytokine expression. Converts resolvins E1, D1 and D2 to their oxo products, which represents a mode of resolvin inactivation. Resolvin E1 plays important roles during the resolution phase of acute inflammation, while resolvins D1 and D2 have a unique role in obesity-induced adipose inflammation.
Synonyms: 15-PGDH; PGDH1; SDR36C1; PGDH; PHOAR1
Tractability: Small molecule: a structure with a bound ligand is known; a high-quality ligand is known; it has a high-quality binding pocket; it belongs to a druggable protein family. PROTAC: ubiquitination databases record sites on it; a small molecule that binds it is known.
Target class: Enzyme; Oxidoreductase
Chemical probes: ML-148, ML149, ML387, ML388, PD080993, PD081325, PD081787, PD082115, PD083066, PD084402, PD085304, STK393606
Gene: Protein-coding gene on chromosome 4 (174,490,175 to 174,523,154, reverse strand). Ensembl gene ENSG00000164120.
Subcellular location: Cytoplasm
Subcellular location (Human Protein Atlas): Cytosol; Nucleoplasm
Pathways (Reactome):
Metabolism: Biosynthesis of D-series resolvins; Biosynthesis of E-series 18(S)-resolvins; Biosynthesis of Lipoxins (LX); Synthesis of Prostaglandins (PG) and Thromboxanes (TX)
Gene Ontology:
Molecular function: 15-hydroxyprostaglandin dehydrogenase (NAD+) activity; identical protein binding; NAD binding; NAD+ binding; oxidoreductase activity, acting on the CH-OH group of donors, NAD or NADP as acceptor; prostaglandin E receptor activity; 15-hydroxyicosatetraenoate dehydrogenase activity
Biological process: female pregnancy; negative regulation of cell cycle; parturition; prostaglandin metabolic process; regulation of prostaglandin catabolic process; transforming growth factor beta receptor signaling pathway; ductus arteriosus closure; lipoxygenase pathway; ovulation; thrombin-activated receptor signaling pathway; kidney development; lipoxin biosynthetic process; positive regulation of apoptotic process; positive regulation of vascular associated smooth muscle cell proliferation; prostaglandin catabolic process; response to estradiol; response to ethanol; response to lipopolysaccharide
Cellular component: cytosol; extracellular exosome; cytoplasm; basolateral plasma membrane; extracellular region
Genetic constraint (gnomAD): Loss-of-function variants: 10 observed, 13.25 expected, observed/expected ratio (o/e) 0.75, 90% interval 0.47 to 1.28. The upper end of that interval is the gene's LOEUF score, 1.28, which puts it in group 5 of 6, group 1 being the genes least tolerant of losing a copy. Missense variants: 158 observed, 145.06 expected, observed/expected ratio (o/e) 1.09, 90% interval 0.96 to 1.24. Synonymous variants: 52 observed, 52.97 expected, observed/expected ratio (o/e) 0.98, 90% interval 0.79 to 1.24.
Homologues: Orthologues: chimpanzee HPGD (100% identical), macaque HPGD (99% identical), dog HPGD (94% identical), pig HPGD (94% identical), rabbit HPGD (93% identical), mouse Hpgd (89% identical), rat Hpgd (88% identical), guinea pig HPGD (85% identical), zebrafish hpgd (55% identical), Drosophila melanogaster Pdh (30% identical), Drosophila melanogaster CG18814 (30% identical), Drosophila melanogaster CG4842 (30% identical), and 3 more.
Diseases named in the same sentence as HPGD in open-access papers:
HPGD is named in the same sentence as 123 diseases in open-access papers, as found by Europe PMC text mining. Sharing a sentence is not in itself a finding about the gene and the disease. The quoted sentences say what the papers report.
breast carcinoma (22 papers, 2011 to 2025). "In breast cancer, HPGD expression has been positively associated with estrogen receptor (ER) and tumor stages, suggesting a potential tumor-promoting role." (PMID 40076539, 2025). "HPGD, which encodes alcohol dehydrogenase, was reported as a marker of poor prognosis of breast cancer." (PMID 36077333, 2022). "In clinically more aggressive primary breast cancers, particularly those with a triple negative phenotype, and in breast cancer metastases, HPGD is overexpressed, with high HPGD expression associated with poor prognosis and reduced survival." (PMID 33210098, 2020). "HPGD downregulation in breast cancer is associated with reduced response to TAM therapy via PGE2-EP4 signalling and decreases patient survival." (PMID 33210098, 2020). "Building on our previous data, the aim of this study was to investigate a causal link between HPGD expression and function and TAMr, as well as explore the relationship between HPGD expression in breast cancer samples and clinical outcomes." (PMID 33210098, 2020). "We then tested the association between each of the listed miRNAs and HPGD mRNA levels in 987 breast cancer samples from the TCGA database using OncoLnc where both miRNA and mRNA expression data were available." (PMID 33210098, 2020). "Decreased HPGD expression was associated with decreased overall survival in ERα-positive breast cancer patients." (PMID 33210098, 2020). "It has been reported that HPGD is associated with various types of cancer, such as bladder cancer, gastrointestinal cancer, breast cancer, and cervical cancer 44-47." (PMID 31692912, 2019). "Noticeably, a recent study showed that the miR-485-5p binding site, SNP rs8752, in the HPGD gene was associated with breast cancer risk." (PMID 27010860, 2016). "The A allele cannot be targeted by miR-485-5p, which will result in the increase of HPGD protein expression, a possible underlying mechanism for the observed association with the risk of breast cancer." (PMID 25003827, 2014). "Ido Wolf at al. reported that HPGD was an epigenetically silenced tumor suppressor gene in breast cancer and there was an association between HPGD expression and the ER pathway activity." (PMID 25003827, 2014). "In summary, our findings suggested that common variants in the HPGD gene might be associated with breast cancer risk among Chinese women." (PMID 25003827, 2014). "Genes identified included novel genes such as HPGD, FASN and KRT81, as well as SCIN and TPM1 which have already been confirmed in acquired drug resistance mechanisms associated with HER2-positive breast cancer." (PMID 40946111, 2025). "This ambiguity emphasizes the need for a more comprehensive understanding of HPGD’s function in breast cancer, particularly in TNBC, where its precise role remains poorly defined." (PMID 40076539, 2025). "In breast cancer, the epigenetic regulation of the HPGD gene modulates the activity of the ER pathway." (PMID 38139172, 2023). "HPGD is an enzyme that converts PGE2 to 15-keto-PGE2 and has been associated with epithelial-to-mesenchymal transition and poor survival of patients with breast cancer and lung cancer." (PMID 34741119, 2022). "In the context of breast cancer, HPGD acts as a tumor suppressor, and the upregulation of HPGD was found to reduce tumorigenesis in athymic mice." (PMID 35317779, 2022). "Studies in breast cancer are contradictory; higher HPGD expression has been reported in ERα-positive MCF-7 cell with reduced expression in ERα-negative MDA-MB-231 cells, where up-regulation was observed following treatment with demethylating agents." (PMID 33210098, 2020). "Some studies of HPGD expression in breast tissues have demonstrated higher expression in normal breast tissue than breast cancer, supporting a tumour suppressive role." (PMID 33210098, 2020).
breast carcinoma (continued). "We analysed the relationship between HPGD expression and clinical outcome for breast cancer patients using the on-line resource Kmplot and from our own cohort of breast cancer patient’s data in separate survival analyses." (PMID 33210098, 2020). "HPGD overexpression and silencing studies were performed in isogenic TAMr and parental human breast cancer cell lines to establish the impact of HPGD expression on TAM resistance." (PMID 33210098, 2020). "The authors previously reported that 15-hydroxyprostaglandin dehydrogenase (HPGD) was significantly downregulated in tamoxifen-resistant (TAMr) breast cancer cell lines." (PMID 33210098, 2020). "HPGD (15-PGDH) is highly expressed in normal tissues but is ubiquitously lost in human colon, gastric, lung, and breast cancer." (PMID 24213116, 2011). "However, the role of HPGD, the enzyme responsible for degrading prostaglandins and maintaining homeostasis, remains controversial in breast cancer development." (PMID 40076539, 2025). "High HPGD expression levels are associated with a good prognosis in patients with colon cancer, gastric cancer, lung cancer, and breast cancer, which has led to the hypothesis that HPGD functions as a tumor suppressor." (PMID 40076539, 2025). "Notably, reduced or silenced expression of HPGD in breast cancer leads to elevated PGE2 levels and enhanced tumor progression, supporting its role as a tumor suppressor." (PMID 40076539, 2025). "miR-21 was found to be overexpressed in TAMr cell line compared to TAMs cell lines, which may contribute to HPGD downregulation in TAM resistant breast cancer." (PMID 33210098, 2020). "We have demonstrated a downregulation of HPGD expression in TAM-resistant breast cancer both in vitro in multiple series of TAMs and TAMr isogenic cell line pairs and in clinical samples using retrospective immunohistochemistry studies and in silico approaches." (PMID 33210098, 2020). "There are no data available thus far establishing a direct interaction between miR-3200-3p and HPGD mRNA, however correlation between HPGD and miR-3200-3p in breast cancer cases in the TCGA database using the OncoLnc platform revealed a weak negative correlation." (PMID 33210098, 2020). "Conversely, in rare apocrine breast carcinomas, HPGD was highly expressed." (PMID 33210098, 2020). "In breast cancer cell lines, 4-OXO-DHA induced PPARɣ and 15-hydroxyprostaglandin dehydrogenase (15-PGDH) but inhibited the activity of NF-κB and suppressed PI3K and mTOR signaling." (PMID 33431978, 2021). "HPGD, hydroxyprostaglandin dehydrogenase 15‐(NAD), was found to be abundantly expressed in highly metastatic breast cancer cells, while knockdown of HPGD attenuated aryl hydrocarbon receptor signalling and induced mesenchymal‐epithelial transition." (PMID 33107155, 2020). "Here, the authors investigated the relationship between HPGD expression, TAM resistance and prediction of outcome in breast cancer." (PMID 33210098, 2020). "Furthermore, HPGD expression was lower still in more aggressive basal/triple negative and HER2-positive breast cancers." (PMID 33210098, 2020). "In our study, HPGD overexpression did not reduce intracellular PGE2 levels in human breast cancer cells, which may be due to compensatory mechanisms involving other regulators of PGE2 homeostasis." (PMID 40076539, 2025). "Together, these findings reveal that HPGD exerts diverse, non-enzymatic effects on TNBC tumorigenesis, offering new insights into its complex role in breast cancer biology." (PMID 40076539, 2025).
colon carcinoma (20 papers, 2009 to 2025). "Increased synthesis of PGE2 in CRC has been shown to occur through COX-2-dependent mechanisms; however, loss of the PGE2-catabolizing enzyme, 15-hydroxyprostaglandin dehydrogenase (15-PGDH, HPGD), in colonic tumors contributes to increased prostaglandin levels and poor patient survival." (PMID 30931980, 2019). "Additionally, HPGD activity was absent in lung adenocarcinoma and colon cancer cells." (PMID 26082314, 2015).
colorectal cancer (12 papers, 2012 to 2025). A primary or metastatic malignant neoplasm that affects the colon or rectum. "There was no significant change in COX‐1 and 15‐hydroxyprostaglandin dehydrogenase (15‐PGDH) in subjects at normal risk for colorectal cancer." (PMID 36789081, 2023). "The loss expression of HPGD was reported in several colorectal carcinoma cell lines and microscopic colon adenomas." (PMID 37091184, 2023). "Genotype frequencies among cases and controls and risk estimates for the involvement of COX-2/HPGD/SLCO2A1/ABCC4 polymorphisms in colorectal cancer onset." (PMID 24694755, 2014). "Risk estimates for the involvement of polymorphisms in COX-2/HPGD/SLCO2A1/ABCC4 genes in colorectal cancer onset stratified by sex, smoking habits and body mass index." (PMID 24694755, 2014). "We and others have shown that colorectal cancer patients with elevated cysteinyl leukotriene receptor 2 (CysLT2R) and 15-hydroxyprostaglandin dehydrogenase (15-PGDH) levels exhibit good prognoses." (PMID 32814764, 2020). "Elevated tissue levels of PGE-2, whose production is regulated by COX-1 and NAD+-dependent 15-hydroxyprostaglandin dehydrogenase (15-PGDH), are an early event in colorectal cancer." (PMID 27529277, 2016). "Additionally, earlier research by others has demonstrated an association between the down-regulation of 15-Hydroxyprostaglandin dehydrogenase (15-PGDH) expression and activity in colorectal cancer and the generation of the urinary PGE2 metabolite PGE-M." (PMID 36923425, 2023).
gastric cancer (11 papers, 2014 to 2025). A primary or metastatic malignant neoplasm involving the stomach. "15-hydroxyprostaglandin dehydrogenase (15-PGDH), the rate-limiting enzyme in prostaglandin E2 degradation, is decreased in gastric cancers and microRNA (miR)-21 is one of the regulators." (PMID 30531928, 2018). "In gastric cancer cells, COX-2 deletion upregulates 15-hydroxyprostaglandin dehydrogenase (15-PGDH), an enzyme responsible for PGE2 degradation." (PMID 26452035, 2015). "The expression of HPGD was absent in colonic mucosa and gastric carcinoma." (PMID 26082314, 2015).
prostate carcinoma (11 papers, 2010 to 2025). A carcinoma that arises from epithelial cells of the prostate gland. "HPGD expression is induced by androgen and is up-regulated in the androgen-dependent prostate cancer cell line LNCaP49." (PMID 32103057, 2020). "We found one amplified gene in the in-frame fusion samples, hydroxyprostaglandin dehydrogenase 15-(NAD) (HPGD), which was reported as a therapeutic target in prostate cancer due to its involvement in the arachidonic acid pathway with PLA2G7, EPHX2, and CYP4F8." (PMID 29299133, 2017). "In prostate cancer, the genes PLA2G7, HPGD, EPHX2, and CYP4F8 exhibit significantly altered expression." (PMID 38172792, 2024). "Six target genes were subjected to protein validation: GPR116, NPY and PLA2G7, three genes over-expressed in ERG+ tissues, and AZGP1, HPGD and TFF3, three genes down-regulated in ERG+ prostate cancer tissues." (PMID 23390522, 2013). "In prostate cancer cells, calcitriol reduces the expression levels of COX-2 and that of PG receptors EP2 and FP, whereas it increases the expression of 15-hydroxyprostaglandin-dehydrogenase (15-PGDH), a NAD+-dependent enzyme responsible for the degradation of PGE259,60." (PMID 29657326, 2018). "Protein levels of the target genes GPR116 and HPGD were not altered on comparison of ERG+ and ERG− prostate cancer (data not shown)." (PMID 23390522, 2013).
colitis (10 papers, 2017 to 2025). Inflammation of the colon. "However, HPGD (15-PGDH, HGNC: 5154) protein is significantly downregulated in colorectal tumors, and genetic ablation of this enzyme promotes colitis and polyp formation in mouse models." (PMID 40958118, 2025). "Additionally, our laboratory has shown that Se supplementation leads to the upregulation of 15-hydroxyprostaglandin dehydrogenase (15-PGDH), the enzyme that oxidizes PGE2, and a subsequent decrease in PGE2 during DSS-induced colitis leading to the resolution of inflammation." (PMID 29494512, 2018).
lung carcinoma (8 papers, 2014 to 2025). "In xenograft mouse models using human lung cancer cells, HPGD overexpression has been shown to decrease tumor growth, suggesting a tumor-suppressive role of the enzyme in certain contexts." (PMID 40076539, 2025). "Interestingly, in this lung cancer model, HPGD overexpression induced epithelial-to-mesenchymal transition (EMT) in cancer cells, which contributed to tumor promotion." (PMID 40076539, 2025). "To substantiate our results by 6-AN treatment in lung cancer cells, we checked the expression of PPP-related genes such as G6PD, HPGD, TKT, and TALDO1 in these cells 48 h after 6-AN treatment." (PMID 34827081, 2021). "These analyses demonstrated that mRNA expression of G6PD, glutaminase (GLS), hydroxy-prostaglandin dehydrogenase 15-(NAD) [HPGD], TKT, TALDO1, ribulose-5-phosphate-3-epimerase (RPE), and transketolase-like-1 (TKTL1) were more abundant in lung cancer patient samples." (PMID 34827081, 2021).
primary hypertrophic osteoarthropathy (7 papers, 2011 to 2023). A genetically and clinically heterogeneous inherited disorder characterized by digital clubbing and osteoarthropathy, with variable features of pachydermia, delayed closure of the fontanels, and congenital heart disease. "In conclusion, we describe the reclassification of a variant in the HPGD gene that is associated with primary hypertrophic osteoarthropathy." (PMID 37591693, 2023). "In primary hypertrophic osteoarthropathy (pachydermoperiostosis), gene-mutations of the prostaglandin degrading enzyme, 15-hydroxyprostaglandin dehydrogenase (HPGD) and the PG transporter (SLCO2A1) lead to impairment of PGE2 degradation." (PMID 37814319, 2023). "Primary hypertrophic osteoarthropathy (PHO) is a rare disease related to HPGD and SLCO2A1 gene mutation." (PMID 31878983, 2019). "The pathogenic variations in HPGD cause primary hypertrophic osteoarthropathy (PHO), inherited in an autosomal recessive mode." (PMID 37980516, 2023). "Here, we highlight the case of a 31-yr-old man who had clinical features of primary hypertrophic osteoarthropathy (PHOAR) and harbored a homozygous variant (c.38C > A, p.Ala13Glu) in the HPGD gene, as indicated by whole-exome sequencing (WES)." (PMID 37591693, 2023). "Remarkably, inherited mutations in HPGD gene are linked to the development of primary hypertrophic osteoarthropathy (PHO), thus reinforcing the impact that the genetic variability in HPGD might portray in disease development by disrupting the normal 15-HPGD levels or activity." (PMID 24694755, 2014).
bladder cancer (6 papers, 2018 to 2025). "Overall, these results suggest that DNA hypermethylation at FBP1 and HPGD loci is associated with their reduced expression, aligning with disease aggressiveness and poor survival in bladder cancer patients." (PMID 40626022, 2025). "Our findings demonstrate a strong inverse correlation between DNA methylation levels at FBP1 and HPGD loci and their gene expression, thereby linking epigenetic dysregulation directly to the tumor aggressiveness in bladder cancer." (PMID 40626022, 2025). "The TF-protein JUN (a regulator of ANGPT1, HPGD, ATF6B and OAS3) is associated with bladder cancer disease." (PMID 35617355, 2022). "For example, in bladder cancer, miR-146b-3p can expedite proliferation and invasion of cancer cells via targeted down-regulation of 15-hydroxyprostaglandin dehydrogenase (HPGD) and neurofibromin 2 (NF2) expressions." (PMID 34115567, 2021). "To this end, we investigated the correlation between DNA methylation and expression of genes from Metab-GS in bladder cancer, and found high inverse correlation (>−0.50) between DNA methylation and expression of tumor suppressor metabolic hubs, FBP1 and HPGD." (PMID 40626022, 2025). "Interestingly, the decrease in levels of protein biomarkers, including adipocyte-type fatty acid-binding protein (aFABP), glutathione S-transferase μ (GST μ), and 15-hydroxyprostaglandin dehydrogenase (PGDH), as well as cytokeratin 13 (CK13), has been described in high-grade human bladder cancer." (PMID 29396722, 2018).